SLC5A9 (solute carrier family 5 member 9)
Description:
Electrogenic Na(+)-coupled sugar symporter that may play a primary role in D-mannose and possibly D-fructose and D-glucose transport at the plasma membrane. Transporter activity is driven by a transmembrane Na(+) electrochemical gradient set by the Na(+)/K(+) pump. Exclusively recognizes sugar substrates having a pyranose ring with an axial hydroxyl group on carbon 2.
Synonyms: SGLT4
Tractability: Small molecule: it belongs to a druggable protein family. Antibody: UniProt places it where antibodies can reach, with high confidence; its Gene Ontology location is reachable by antibodies, with high confidence; UniProt predicts a signal peptide or a membrane-spanning region.
Gene: Protein-coding gene on chromosome 1 (48,222,685 to 48,248,644, forward strand). Ensembl gene ENSG00000117834.
Subcellular location: Cell membrane
Subcellular location (Human Protein Atlas): Actin filaments; Cytosol
Pathways (Reactome):
Transport of small molecules: Cellular hexose transport
Gene Ontology:
Molecular function: low-affinity D-glucose:sodium symporter activity; transmembrane transporter activity; carbohydrate:monoatomic cation symporter activity; hexose transmembrane transporter activity; solute:sodium symporter activity
Biological process: hexose transmembrane transport; sodium ion transmembrane transport; transmembrane transport
Cellular component: extracellular exosome; plasma membrane; membrane
Genetic constraint (gnomAD): Loss-of-function variants: 55 observed, 70.09 expected, observed/expected ratio (o/e) 0.78, 90% interval 0.63 to 0.98. The upper end of that interval is the gene's LOEUF score, 0.98, which puts it in group 4 of 6, group 1 being the genes least tolerant of losing a copy. Missense variants: 804 observed, 899.82 expected, observed/expected ratio (o/e) 0.89, 90% interval 0.84 to 0.95. Synonymous variants: 332 observed, 358.92 expected, observed/expected ratio (o/e) 0.93, 90% interval 0.85 to 1.01.
Homologues: Orthologues: chimpanzee SLC5A9 (99% identical), macaque SLC5A9 (96% identical), rabbit SLC5A9 (88% identical), pig SLC5A9 (87% identical), rat Slc5a9 (87% identical), mouse Slc5a9 (85% identical), dog SLC5A9 (85% identical), tropical clawed frog slc5a9 (70% identical), zebrafish slc5a9 (68% identical), Drosophila melanogaster rumpel (19% identical), Drosophila melanogaster bumpel (17% identical), Drosophila melanogaster CG31668 (17% identical), and 9 more. Paralogues in human: SLC5A10 (54% identical), SLC5A1 (53% identical), SLC5A2 (53% identical), SLC5A4 (49% identical), SLC5A11 (48% identical), SLC5A3 (47% identical), SLC5A8 (21% identical), SLC5A12 (20% identical), SLC5A5 (19% identical), SLC5A6 (19% identical), SLC5A7 (14% identical).
Diseases named in the same sentence as SLC5A9 in open-access papers:
SLC5A9 is named in the same sentence as 14 diseases in open-access papers, as found by Europe PMC text mining. Sharing a sentence is not in itself a finding about the gene and the disease. The quoted sentences say what the papers report.
Hypertension (2 papers, 2025). The presence of chronic increased pressure in the systemic arterial system. "Secondly, we have found a protective recessive association between a missense variant in solute carrier (SLC) family 5 member 9 (SLC5A9) (chr1:48228922G>A, rs61746559) hypertension (OR = 0.2, p = 3 × 10−8, dominance deviation p = 7 × 10−6)." (PMID 40306283, 2025).
cholestasis (1 paper, 2017). Impairment of the bile flow caused by obstruction within the liver, or outside the liver in the bile duct system. "SLC5A9 (inhibition) was the most affected starting node at 2 h of treatment, which suggests that down-regulation of SLC5A9 is a potential MIE in an AOP for fibrosis, cholestasis or liver cancer." (PMID 28032149, 2017).
dyslipidemia (1 paper, 2021). "However, there are reports on six of Slc genes (Slc2a10, Slc5A1, Slc5a9, Slc6A14, Slc16A5, Slc25A24) in metabolic diseases including obesity, dyslipidemia, NAFLD, and T2DM." (PMID 34659115, 2021).
proliferative diabetic retinopathy (1 paper, 2021). Advanced retinopathy due to diabetes mellitus characterized by the formation of new vessels in the retina. "A mutation within Slc5a9 gene is reported in the development of proliferative diabetic retinopathy." (PMID 34659115, 2021).
SLC5A9 also shares sentences with these, for which no sentence is quoted: infection (3 papers); cancer (1); cardiovascular disease (1); chronic kidney disease (1); hyperandrogenemia (1); liver cancer (1); metabolic disease (1); neutropenia (1); Obesity (1); Right ventricular cardiomyopathy (1).